KRTAP27-1 (keratin associated protein 27-1)
Description:
In the hair cortex, hair keratin intermediate filaments are embedded in an interfilamentous matrix, consisting of hair keratin-associated proteins (KRTAP), which are essential for the formation of a rigid and resistant hair shaft through their extensive disulfide bond cross-linking with abundant cysteine residues of hair keratins. The matrix proteins include the high-sulfur and high-glycine-tyrosine keratins.
Tractability: No criterion of Open Targets' tractability assessment is met for any kind of drug.
Gene: Protein-coding gene on chromosome 21 (30,337,013 to 30,337,694, reverse strand). Ensembl gene ENSG00000206107.
Pathways (Reactome):
Developmental Biology: Keratinization
Gene Ontology:
Molecular function: structural molecule activity
Cellular component: cytosol; keratin filament
Genetic constraint (gnomAD): Loss-of-function variants: 3 observed, 1.73 expected, observed/expected ratio (o/e) 1.74, 90% interval 0.61 to 1.94. That is too few expected variants to judge how well the gene tolerates losing a copy. Missense variants: 264 observed, 257.07 expected, observed/expected ratio (o/e) 1.03, 90% interval 0.93 to 1.14. Synonymous variants: 103 observed, 94.16 expected, observed/expected ratio (o/e) 1.09, 90% interval 0.93 to 1.29.
Homologues: Orthologues: chimpanzee KRTAP27-1 (96% identical), macaque KRTAP27-1 (89% identical), dog KRTAP27-1 (62% identical), pig KRTAP27-1 (59% identical), guinea pig KRTAP27-1 (54% identical), mouse Krtap27-1 (51% identical). Paralogues in human: KRTAP11-1 (23% identical), KRTAP26-1 (22% identical), KRTAP13-1 (22% identical), KRTAP13-2 (21% identical), KRTAP13-3 (19% identical), KRTAP13-4 (18% identical), KRTAP15-1 (15% identical), KRTAP25-1 (8% identical).